RNU6-1301P (RNA, U6 small nuclear 1301, pseudogene)
Gene: Small nuclear RNA gene on chromosome 3 (37,140,327 to 37,140,430, forward strand). Ensembl gene ENSG00000199594.
Homologues: Orthologues: chimpanzee U6 (99% identical), macaque U6 (93% identical), mouse Gm25524 (86% identical), dog U6 (70% identical). Paralogues in human: RNU6-41P (87% identical), RNU6-44P (87% identical), RNU6-1152P (86% identical), RNU6-393P (86% identical), RNU6-869P (86% identical), RNU6-880P (86% identical), RNU6-1181P (85% identical), RNU6-12P (85% identical), RNU6-13P (85% identical), RNU6-16P (85% identical), RNU6-25P (85% identical), RNU6-310P (85% identical), and 1286 more.